IL6 (interleukin 6)
Diseases named in the same sentence as IL6 in open-access papers (continued):
Sharing a sentence is not in itself a finding about the gene and the disease.
COVID-19 (continued). "A broad range of clinical biomarkers, such as total leukocyte levels, lymphocyte and neutrophil measurements, along with inflammatory markers like CRP, PCT, and IL-6, have been thoroughly explored in prior research and linked to both the progression and fatal outcomes of COVID-19." (PMID 41309368, 2025). "In addition, cytokines and chemokines associated with neutrophil chemoattraction such as CXCL8 and IL-6 are associated with severe COVID-19." (PMID 41279061, 2025). "COVID-19-associated myocarditis is caused by direct cell injury and T-lymphocyte-mediated cytotoxicity, possibly being augmented by cytokine storm syndrome, especially by interleukin 6 (IL-6)." (PMID 40509126, 2025). "Additionally, invasive mechanical ventilation, renal transplant therapy, and treatment of COVID-19 with interleukin-6 inhibitors and corticosteroids also increase the risk of CAPA." (PMID 40172196, 2025). "The systemic inflammatory response associated with acute COVID-19, characterized by an exaggerated release of pro-inflammatory cytokines, such as IL-6 and TNFα, may disrupt protein turnover and muscle mass loss." (PMID 40283747, 2025). "Moreover, cytokine release syndrome characterized by TNF-α, IL-6, and IL-1β was associated with disease severity and, higher levels of IL6 were more predictive for COVID-19 mortality." (PMID 40121473, 2025). "Interleukin-6 (IL-6) is a critical cytokine involvedin immuneregulation, inflammation, and the pathogenesis of various diseases,including autoimmune disorders, cancer, and the cytokine storm associatedwith severe COVID-19." (PMID 39967508, 2025). "Both findings underline the role of IL-6 in the assessment of severe COVID-19." (PMID 39210228, 2025). "A possible explanation for this difference is the higher proportion of patients with moderate and severe forms of COVID-19 in our group, as these forms are generally associated with a heightened inflammatory response, reflected by increased levels of IL-6, IL-1, and LDH." (PMID 40333079, 2025). "Additionally, high levels of IL-6, as observed in various COVID-19 studies, correlate with predictive mortality and association with respiratory failure, shock, and severe symptoms in hospitalized patients." (PMID 40506975, 2025). "A special and obvious suspect is IL-6 due to its role in COVID-19-associated inflammation." (PMID 41375068, 2025). "However, studies have shown that tocilizumab, by inhibiting the action of IL-6, is associated with increased survival in patients severely affected by COVID-19." (PMID 40564052, 2025). "Additionally, IgG4 levels correlate with IL-6 levels, a known risk factor for mortality associated with COVID-19." (PMID 40872876, 2025). "Additionally, we tried to incorporate the cytokine storm mechanism through IL-6 action, a hallmark of critical COVID-19 cases often requiring mechanical ventilation." (PMID 40431602, 2025). "Moreover, elevated interleukin-6 (IL-6), associated with the host immune response, has been found to be associated with COVID-19 severity." (PMID 40687705, 2025). "This study significantly advances our understanding of COVID-19 severity by evaluating a comprehensive panel of cytokines and clinical markers, confirming the robust association between elevated levels of IL-1β, IL-6, IL-8, IL-10, IL-17A, IL-23, TNF-α, and IFN-α with critical disease outcomes." (PMID 39861879, 2025). "Similarly, chronic inflammatory states are associated with excessive production of TNF-α, IL-6, and IL-1β, which occurs in severe forms of COVID-19, as well as in RA and chronic per-iodontitis." (PMID 41614780, 2025). "Additionally, significantly higher IL-6 levels were associated with the concomitant presence of COVID-19 and Self-RPD+, as well as with nasal congestion." (PMID 40647649, 2025). "The IL-6/KL-6 value in COVID-19 patients might be valuable to speed-up diagnostic workflow in symptomatic and hypoxemic patients in whom transfer to the CT facility is sometimes risky." (PMID 40397955, 2025).
COVID-19 (continued). "Moreover, the study reveals consistent results for crucial biomarkers, such as IL-6 and S100B, exhibiting low variability (I2 < 30%) among the studies, which suggests dependable associations with COVID-19 severity, particularly in pneumonia cases." (PMID 41585373, 2025). "In our study, we described the demographical and clinical characteristics of patients with COVID-19 stratified by severity and assessed associations to infer the potential use of inflammatory cytokines (IL-2, IL-4, IL-6, IL-8, IL-10, TNF-α, GM-CSF, and IFN-γ) as biomarkers of COVID-19 pneumonia." (PMID 40508859, 2025). "Diabetes, especially in the presence of hyperglycemia, significantly influences the severity of COVID-19 symptoms, possibly due to the association between hyperglycemia and elevated levels of IL-6 and IL-6 receptors, indicative of severe lung disease in COVID-19 patients." (PMID 40026986, 2025). "SARS-CoV-2 infection induces the release of proinflammatory cytokines, including IL-1β and IL-6, which may contribute to the development of interstitial pneumonia, a hallmark of severe COVID-19." (PMID 40406515, 2025). "The overexpression of inflammatory molecules, particularly IL-6 and IL-17, in periodontitis may create an environment conducive to increased COVID-19 susceptibility and severity." (PMID 40647649, 2025). "This is interesting because IL-6 was found to be strongly associated with COVID-19 outcome." (PMID 40397955, 2025). "Additionally, the protected animals also exhibited a significant down-regulation in the RNA levels of other important inflammatory mediators such as Il-6 and Il-10, which have been associated with COVID-19 disease progression and severity." (PMID 39087555, 2024). "Moreover, the inference predicted that the possible effects of IL-8 and IL-6 signaling included processes associated with severe COVID-19, such as microvascular dysfunction (HOIP:0039281) and thrombus formation in the lung (HOIP:0041811)." (PMID 38729991, 2024). "The contemporary changes in IL-6 and receptor concentration, as well as the consequent increase in signalling transduction, are closely associated with increased mortality and unfavourable outcomes in COVID-19 patients." (PMID 39063569, 2024). "It is worth mentioning that the IL-6 threshold identified in our analysis (27.9 pg/mL) is of similar extent to that (18 pg/mL) identified in a previous study carried out among COVID-19 adult patients who were associated with impaired CYP3A4-mediated darunavir clearance after CART analysis." (PMID 39065156, 2024). "In particular, interleukin (IL)-6 seems to play an important role in driving this cytokine release, and thus, increased levels have been recognised as a hallmark inflammatory signature in the sera of COVID-19 patients." (PMID 39063569, 2024). "However, in our previous study with the same samples, AUCs for other markers well known for their association with outcomes in COVID-19, such as IL-6, were validated." (PMID 38243237, 2024). "Regarding IL-6 blockade with tocilizumab in COVID-19-associated MAS, the results are controversial." (PMID 39066167, 2024). "Both patients with active AOSD or with severe coronavirus disease-2019 showed elevated Gal-3 and cytokines, including IL-1β, IL-6, and IL-18, supporting a common link of cytokine storm in their pathogenesis." (PMID 38711500, 2024). "High levels of IL-6 in patients with COVID-19 may be associated with an imbalance in the differentiation of naive T cells." (PMID 39457048, 2024). "Research shows that thyme and its bioactive compounds can suppress pro-inflammatory cytokines (e.g., TNF-α, and IL-6) and boost anti-inflammatory cytokines like IL-10, which may help manage inflammation linked to COVID-19." (PMID 39683135, 2024). "Several studies have shown that IL-6 is closely associated with the onset and severity of COVID-19." (PMID 39717543, 2024).
COVID-19 (continued). "Of note, the IL-6 level in CSF was much higher (> 750 times) than serum levels, suggesting that persistent intracranial inflammation raised a risk for the rupture of a preexisting aneurysm after COVID-19." (PMID 38166683, 2024). "In addition, persistent fever, elevated levels of CRP, interleukin-6, and procalcitonin led us to consider a potential association with COVID-19-related MIS in adults, where IBD was the predominant presentation." (PMID 38669420, 2024). "Additionally, it has been reported that elevated IL-6 levels are significantly associated with severity in patients with COVID-19." (PMID 39351097, 2024). "However, cells from COVID-19 patients with the C allele significantly increase cytokine production when stimulated with spike + LPS, mainly IL-10, IL-6, and TNF-α compared to the unstimulated condition." (PMID 39456843, 2024). "However, for patients with moderate to severe risk for OSA with concurrent COVID-19, there is a decrease in serum IL-6, Eotaxin-1/CCL11, and salivary MIP-3α/CCL20." (PMID 38476500, 2024). "The role of polymorphisms in genes encoding IL-6 in the severity of COVID-19 is unclear." (PMID 39354444, 2024). "Together, several studies were able to detect associations of IL-6 pathway genes with COVID-19 severity, long COVID development, as well as with antibody response, highlighting IL-6 pathway SNPs as relevant candidate genetic markers in COVID-19 aspects, including in IgG response duration." (PMID 39201427, 2024). "Visceral adipose tissue is more metabolically active than subcutaneous adipose tissue and secretes a variety of adipokines and pro-inflammatory cytokines, including interleukin 6 (IL-6) leptin, which is associated with the severity of pulmonary inflammation in COVID-19 patients." (PMID 39311212, 2024). "Consequently, COVID-19 is associated with systemic inflammation and elevated interleukin 6 levels, resulting in reduced lymphocyte counts." (PMID 39130863, 2024). "Considering that previous studies have shown contradictory roles—protective and adverse—for IL-6 in viral lung infections, it is possible that the effect of IL-6 on COVID-19 has a protective or pathogenic role depending on cytokine levels before and during the disease." (PMID 39062668, 2024). "Moreover, significantly increased IL6 levels were determined in COVID-19-infected hospitalized patients, often linked to hyperglycemia." (PMID 39457607, 2024). "Moreover, LMWH was associated with a significant reduction in IL-6 levels in COVID-19 patients and appeared to have inhibitory properties against heparanase." (PMID 38753622, 2024). "The gene expression levels of cGAS, STING and the plasma levels of the cytokines IFN-α, TNF-α and IL-6 in patients with acute COVID-19 were evaluated according to factors considered risk factors for the severity of the disease, namely, sex, age and comorbidities." (PMID 38424312, 2024). "Our studies suggest that the increased susceptibility of COVID-19 patients to delirium is attributable to the known effect of the virus inducing high levels of circulating IL-6—and that blocking IL-6 activity in the blood may ameliorate delirium." (PMID 38778074, 2024). "In COVID-19 patients, the level of inflammatory cytokines is increased and plays a crucial role in the pathogenesis of the disease; among them, interferon-γ (IFNγ), TNFα, IL-1β and IL-6 are indicated as the key cytokines associated with the severity of COVID-19." (PMID 38542436, 2024). "Low-level heteroplasmy was significantly elevated in COVID-19 patients, especially in genes of the respiratory complex I. Both heteroplasmic variant burden and low-level heteroplasmy were associated with increased levels of IL-6, TNF-α, and IFN-α." (PMID 38377022, 2024). "Hepcidin, ferritin, CRP, and IL-6 are predictive parameters of critical COVID-19 occurrence, and extremely high levels of IL-6 are strongly associated with the presence of septic shock or sepsis in COVID-19 patients." (PMID 39457607, 2024).
COVID-19 (continued). "However, less is known about the relationship between pre-COVID-19 IL-6 levels and the risk of severe COVID-19." (PMID 39062668, 2024). "IL-6 is a pro-inflammatory cytokine and has previously been linked with COVID-19 severity." (PMID 38730063, 2024). "To explore the mechanisms of decreased expression of PD-1 in CD4+ and CD8+ T cells from convalescent COVID-19 patients, we measured plasma cytokines associated with PD-1 expression, including IL-2, IL-6, IL-7, IL-10, IL-12p70, IL-33, IFN-γ and CCL19/MIP-3, by Luminex." (PMID 38424104, 2024). "The expression of Zonulin, a protein that regulates tight junction formation in the GIT, is reported to increase the levels of the inflammation marker IL6 and is associated with impaired intestinal barrier function in COVID-19 patients; that also exhibit an increased rate of mortality." (PMID 38863829, 2024). "Among the 19 potential variables, percutaneous oxygen saturation (SpO2) <92% (odds ratio [OR] 7.50, 95% confidence interval [CI] 2.806–20.82) and IL-6 (OR 1.021, 95% CI 1.010–1.033) were included in developing the risk score, which was termed interleukin (IL)-6-based COVID-19 severity (IBC-S) score." (PMID 38394183, 2024). "Similarly, SARS-CoV-2 infection triggers an important IL-6 response, which plays a central role in the cytokine storm associated with severe COVID-19." (PMID 39599491, 2024). "In COVID-19, interleukin 6 (IL-6) causes elevated levels of fibrinogen and tissue factor (TF)." (PMID 39885991, 2024). "Our findings provide valuable insights into the pathogenesis of COVID-19, suggesting that genetic variations at the IL-6 gene may contribute to the susceptibility to severe SARS-CoV-2 infection within the Moroccan population." (PMID 38783290, 2024). "Notably, elevated levels of IL-6 were associated with a higher risk of mortality and the development of acute pancreatitis in COVID-19 patients." (PMID 38397885, 2024). "The complications, severity, and mortality of COVID-19 patients are caused by excessive activation of cytokines (IL-1, IL-6, TNF-a, CCL2, and CXCL10, etc.), namely cytokine storm, which is remarkably similar to the pathogenesis of immune disorders in RA patients." (PMID 38378889, 2024). "Severe COVID-19 cases have been associated with a cytokine storm featuring increased levels of proinflammatory cytokines like interleukin (IL)-1, IL-6, and tumor necrosis factor (TNF)-α, which may promote neuroinflammation and neurodegeneration." (PMID 39456822, 2024). "High levels of IL-6 could be a possible cause of decreased expression of monocyte HLA-DR in patients with severe COVID-19." (PMID 38268832, 2024). "All features were categorical variables, and seven factors were significantly associated with the risk of COVID-19 death, including age, IL-6, blood urea nitrogen (BUN), lactate dehydrogenase (LDH), D-dimer, neutrophil count, and neutrophil-to-lymphocyte ratio (NLR)." (PMID 38961438, 2024). "Studies of COVID-19 convalescents 3–5 months post-infection have revealed maintained high levels of IL-6 associated with persistence of symptoms and a study of autoantibody levels in serum found a high frequency of antibodies against the skin, skeletal muscle and cardiac tissue." (PMID 38212801, 2024). "IL-6 is a multifunctional cytokine that regulates humoral and cellular responses, and has been identified in many previous studies as an important biomarker associated with adverse clinical outcomes of COVID-19." (PMID 38961438, 2024). "On the other hand, EVs may block IL-6, a pro-inflammatory cytokine associated with severe COVID-19, and protect PwCF from adverse outcomes." (PMID 38612524, 2024). "Moreover, the correlation and impact of miR-9 on the expression of pro-inflammatory cytokines IL-6, IL-1β, and TNFα, which are critical mediators in the inflammatory response associated with COVID-19 severity, were also assessed." (PMID 39201618, 2024).
COVID-19 (continued). "In the absence of the S protein, the Con A-stimulated PBMC showed the expected, donor-variable production of IFN-γ, a main mediator of Th1 responses, and IL-6, a cytokine which concurs with inflammation and the dangerous cytokine storm associated with COVID-19." (PMID 38675840, 2024). "Additionally, vitamin D suppresses the production of pro-inflammatory cytokines like interleukin-6 and tumor necrosis factor-alpha, potentially mitigating the cytokine storm associated with severe COVID-19 cases." (PMID 39564063, 2024). "In addition, expression of IL-6, another proinflammatory marker associated with poor outcomes in COVID-19 patients, was suppressed in E7449-treated animals." (PMID 40295745, 2024). "Moreover, Drost’s study demonstrates that IL-6 and its downstream pathways are causally linked to endothelial glycocalyx (eGC) damage in inflammatory conditions, including COVID-19 and bacterial sepsis." (PMID 39518964, 2024). "The IL-6-JAK-STAT3 axis is significantly linked to the onset of severe COVID-19." (PMID 38628843, 2024). "Furthermore, models integrating IL-6 signaling factors were reported to be better than separate component analyses, regarding their diagnostic and prognostic efficacy in COVID-19 patients." (PMID 39452786, 2024). "Moreover, it has been described that the sustained elevation of IL-6 and other cytokines is associated with death in severe COVID-19 cases." (PMID 38601541, 2024). "Therefore, we aimed to evaluate IL-6 and its soluble receptor complex levels in a subset of Delta variant COVID-19 infected patients." (PMID 39063569, 2024). "A genome-wide association study showed that patients with critical COVID-19 had significantly greater blood IL-6 expression levels than patients without symptoms and that an allele change at the rs2069837 site can reduce IL-6 levels to prevent critical conditions." (PMID 38455049, 2024). "In addition to being related to viral infection, studies have shown that the overproduction of IL-6 is associated with lung damage, which can explain why IL-6 receptor blockers are among the most-suggested treatments for COVID-19." (PMID 39583156, 2024). "Elevated IL-6 concentrations are associated with severe outcomes in COVID-19." (PMID 38566026, 2024). "Dynamic fluctuations in serum IL-6, IL-8, and IL-10 levels were linked to patient survival in the intensive care unit and may be used as a biomarker to predict treatment options for COVID-19 patients." (PMID 38544825, 2024). "Hence, inhibition of IL-6 was strategized to obstruct inflammatory responses and manage COVID-19-associated complications." (PMID 37051070, 2023). "Moreover, in patients with COVID-19, a positive correlation observed among IL-6/IL-8, IP-10/IL-6, and IP-10/IL-8 has been linked with a poor prognosis." (PMID 37376437, 2023). "Additionally, a bioinformatics analysis identified the interaction of these lncRNAs with various miRNAs and genes, including inflammation- and COVID-19-associated genes like IL-6, basigin, and MMP9." (PMID 37764186, 2023). "Moreover, the levels of IL-6 have been found to correlate with the severity of COVID-19, which is known to cause ARDS." (PMID 37958192, 2023). "For both TGF-β1 and IL-6 data implying an important role for the course and the outcomes of COVID-19 and may do so concerning the susceptibility." (PMID 37997984, 2023). "A prominent example of IL-6 Amp is also seen in Coronavirus disease 2019 (COVID-19), which is triggered by severe acute respiratory syndrome coronavirus 2 (SARS-CoV2) infection." (PMID 37503036, 2023). "In the recent study, it was found that the decreased expression of uPAR in lung tissues of COVID-19 patients led to the increased level of uPA, which subsequently caused the upregulation of IL-6 and ACE2 expression and significantly promoted PF by inducing EMT of lung epithelial cells." (PMID 37601070, 2023). "IL-6 has recently been implicated as a mediator in COVID-19 neuropsychiatric symptoms." (PMID 37064029, 2023).